DKC1 (dyskerin pseudouridine synthase 1)
Diseases named in the same sentence as DKC1 in open-access papers (continued):
Sharing a sentence is not in itself a finding about the gene and the disease.
tumor (continued). "In addition, the observation that DKC1 mRNA expression in prostate cancer tissues correlated, if only moderately, with hTR levels supports the idea that for the long-term growth of tumours in vivo, dyskerin may additionally be important to maintain telomerase activity." (PMID 19755982, 2009). "The TIDE analysis showed a T Cell exclusion phenotype in DKC1-high tumors, and such immune-cold environment, which was further supported by the TIP evaluation: the diminished trafficking of immune cells into tumor tissues and reduced immune cell infiltration in those tumors." (PMID 40458122, 2025). "In addition, DKC1 and PUS7 expression were negatively correlated with DSS time in nine of the tumor types." (PMID 39162904, 2024). "However, in pituitary tumors, impaired DKC1 function can affect the translation of specific mRNAs containing internal ribosome entry site (IRES) elements, including tumor suppressor p27." (PMID 36770809, 2023). "A similar phenomenon was also observed in the xenograft tumors, wherein DKC1 silencing did not affect the tumor‐promoting function of these ribosomal proteins in DLD‐1 cells in vivo." (PMID 34026451, 2021). "DKC1 mRNA levels were not correlated with tumor telomere length." (PMID 40458122, 2025). "We hypothesize that elevated DKC1 levels increase the production of specific H/ACA snoRNAs and enhance pseudo-uridylation at critical rRNA sites, ultimately altering ribosome composition and function to support tumor progression." (PMID 41510246, 2025). "In addition, the expressions of DKC1, NSUN5, FLNA and CSE1L were validated by qRT-PCR and IHC, and found that DKC1, CSE1L and NSUN5 were highly expressed and FLNA was underexpressed in CRC tumor tissues, consistent with the data in TCGA database." (PMID 36319976, 2022). "Besides, relative DKC1 mRNA expression was increased in CC patients’ tumors, and tumor tissue DKC1 mRNA expression was with negative correlation with miR-197-3p and positive correlation with circ-FLI1." (PMID 35647294, 2022). "The application of the MEK inhibitor trametinib thus could attenuate PF‐induced ERK1/2 phosphorylation in DLD‐1 and HCT116 cells, and we wondered whether the combination of PF (DKC1 inhibitor) and trametinib (MEK inhibitor) could synergistically suppress tumor growth." (PMID 34026451, 2021). "It is noteworthy that we observed only a weak-to-moderate association between DKC1 levels and actual markers of tumour proliferation, such as MKI67 and PCNA, suggesting that the increase in DKC1 expression is not simply a by-product of enhanced cell proliferation." (PMID 19755982, 2009). "The most affected tumor type was PRAD, in which the expression of five synthases, DKC1, PUS3, RPUSD4, PUS7, and TRUB2, had mostly negative effects on DSS." (PMID 39162904, 2024). "The results showed that DKC1 expression was negatively correlated with CD8+ T cells populations at the invasive front, but not at tumor sites and stromal sites." (PMID 36428700, 2022). "Interestingly, the prognostic value of DKC1 was not significant in patients with low expression of SENP3, indicating that SUMOylation statue plays an important role in the DKC1-mediated pro-tumor effect." (PMID 37188742, 2023).
infection (2 papers, 2017 to 2023). The state of being infected such as from the introduction of a foreign agent such as serum, vaccine, antigenic substance or organism. "Analyses of protein–protein interaction networks across modules revealed that xpo1, src, and dkc1 might play crucial roles in the three infected components, and stat, mefv, and tlr13 could have important effects within the first 48 h of infection." (PMID 37570350, 2023).
adenocarcinoma (1 paper, 2021). A common cancer characterized by the presence of malignant glandular cells. "However, the association of DKC1 expression with survival (OS, PFS) of NSCLC patients was not that pronounced as for NOP10, neither in the adenocarcinoma nor in the squamous cell subtype." (PMID 33288886, 2021).
DKC1 also shares sentences with these, for which no sentence is quoted: genetic disorder (3 papers); endometrial carcinoma (2); oral leucoplakia (2); premature aging syndrome (2); Short telomere syndromes (2); Thrombocytopenia (2); acute myeloid leukemia (1); anemia (1); B-cell lymphomas (1); cartilage-hair hypoplasia (1); Chediak-Higashi syndrome (1); chronic mucocutaneous candidiasis (1); Cohen syndrome (1); congenital neutropenia (1); Diamond-Blackfan anemia (1); Down syndrome (1); Dubowitz syndrome (1); head-neck squamous cell carcinoma (1); Hypertension (1); hypogonadism (1); immune deficiency (1); inflammatory bowel disease (1); injury (1); Intellectual disability (1); invasive breast ductal carcinoma (1); metastatic tumors (1); monoclonal gammopathy of undetermined significance (1); multiple myeloma (1); Nail dysplasia (1); non-small cell lung carcinoma (1).
A further 17 diseases each share a sentence with DKC1 in 1 paper.